APP (amyloid beta precursor protein)
Diseases named in the same sentence as APP in open-access papers (continued):
Sharing a sentence is not in itself a finding about the gene and the disease.
Alzheimer disease (continued). "In this manuscript, we used a traditional transgenic model of Alzheimer’s disease, the APP/PS-1 model, to demonstrate discriminatory power of our approach in a mouse model system, which shows clear behavioral deficits in specific tasks, but no reported differences in open-field observation." (PMID 36400882, 2022). "It is tempting to speculate that overexpression of APP, which leads to neurodegeneration in Alzheimer’s disease, may occur in FXS." (PMID 36589236, 2022). "In conclusion, our study uncovers a mechanism by which DNA damage-induced Chk1 activation promotes CIP2A-mediated tau and APP hyperphosphorylation and cognitive dysfunction in Alzheimer’s disease and highlights the therapeutic potential of Chk1 inhibitors in AD." (PMID 35286657, 2022). "Furthermore, in genetic animal models of cognitive impairment such as the APP/PS1 mouse model of Alzheimer’s disease, CEF improved cognitive impairment if administered in the early stage." (PMID 35864981, 2022). "Two genes enriched in Alzheimer’s disease pathway, APP and GSK3β, were further validated." (PMID 35462916, 2022). "Early work showed that injection of Alzheimer’s disease brain homogenates into young APP23 mice overexpressing amyloid precursor protein (APP) resulted in accelerated disease pathology observed by the presence of Aβ plaques at an earlier age than control animals." (PMID 35333865, 2022). "APP is central to the amyloid cascade hypothesis wherein APP is cleaved by β- and γ-secretases to form plaques and amyloid-β (Aβ) peptides, leading to Alzheimer’s disease." (PMID 35432454, 2022). "As adult hippocampal neurogenesis is impaired in Alzheimer’s disease, we tested the hypothesis that sAPPα delivery would rescue adult hippocampal neurogenesis in an APP/PS1 mouse model of Alzheimer’s disease." (PMID 34980189, 2022). "Despite controversy, there is a long-standing hypothesis that early onset Alzheimer’s Disease is a result of the amyloid-β (Aβ) peptide formed from the amyloid beta precursor protein (APP gene)." (PMID 35741010, 2022). "NUMB controls the intracellular trafficking of APP for membrane recycling and thus may be involved in APP metabolism and Alzheimer’s disease pathogenesis." (PMID 35457181, 2022). "Interestingly, AKT1, MAPK8, BCL2L1, FOXO3, and CTNNB1 were not only significantly associated with pathogenic genes (APP, MAPT, and PSEN2) but also with longevity in Alzheimer’s Disease." (PMID 36620771, 2022). "Future work, based on the availability of funding, will be required to perform in vivo studies in transgenic Tau and APP mice to define whether these drugs have therapeutic efficacy against Alzheimer’s Disease mouse models." (PMID 36227739, 2022). "EVs from patients with Alzheimer’s disease were shown to contain tau protein and to be enriched with innate immune response proteins, neuron-specific proteins, and regulators of amyloid precursor protein (APP) metabolism." (PMID 36431078, 2022). "Familial Alzheimer’s disease (FAD) may result from the genetic mutation of genes in the amyloidogenic pathway, such as, amyloid precursor protein; APP and presenilin subunits in the γ-secretase complex; PS1 and PS2." (PMID 36026506, 2022). "In four-month-old APP/PS1 mice with Alzheimer’s disease (AD), it was found that URMC-099 can restore synaptic integrity and hippocampal neurogenesis via facilitating Aβ clearance in the brain, implying multifaceted immune modulatory and neuroprotective roles of URMC-099." (PMID 36142785, 2022). "Alzheimer's disease (AD) is a progressive, irreversible neurodegenerative disorder that pathologically characterizes senile plaque depositions in the brain composed of amyloid‐β (Aβ) produced by sequential cleavage of amyloid precursor protein (APP)." (PMID 35353937, 2022). "To analyze chronic neuroinflammation, we used APP/PS1 mice as a model for Alzheimer’s disease (AD)." (PMID 36040311, 2022).
Alzheimer disease (continued). "The IDP class includes the β-amyloid peptide (Aβ) as one of the sequential proteolysis products of amyloid precursor protein (APP) in Alzheimer’s disease (AD), tau protein in AD and other tauopathies, α-synuclein in Parkinson’s disease (PD), and islet amyloid polypeptide (IAPP) in type II diabetes." (PMID 35646824, 2022). "(iv) Anti-TfR mAb, when fused to erythropoietin, significantly lowered cortical and hippocampal Aβ peptide levels, decreased hippocampal synaptic loss, decreased cortical microglial activation, and improved spatial memory in an APP/PS1 mouse model of Alzheimer’s disease (AD)." (PMID 35884906, 2022). "In Alzheimer’s disease (AD), calpain proteases may be involved in the proteolysis of amyloid precursor protein (APP), which is involved in the formation of amyloid plaques." (PMID 36393840, 2022). "While the full range of functions of APP remains unknown, cleavage of APP generates neurotoxic β-amyloid peptide (Aβ), which accumulates within the brains of individuals with Alzheimer’s disease (AD)." (PMID 35565725, 2022). "The reduction of mushroom spine fractions was shown in PS1-M146V-KI, APP-KI mice models of Alzheimer`s disease (AD), in conditions of low amyloid toxicity, and elimination of mushroom spines has been proposed to underlie the memory loss observed in AD patients." (PMID 35216391, 2022). "ER stress may lead to an accumulation of β-amyloid (Aβ) and amyloid precursor protein (APP), and indeed stimulation of expression of other DnaJ family BiP co-chaperones has been shown to ameliorate the accumulation of Aβ in cellular Alzheimer’s disease models." (PMID 34692675, 2021). "Consistently, the overall m6A level was elevated in the cortex and the hippocampus of APP/PS1 (Alzheimer’s disease) mice compared to C57BL/6 control mice, and FTO was found to interact with APOE, which is associated with Alzheimer’s disease risk in a prospective cohort study." (PMID 33611339, 2021). "In Alzheimer’s disease, hnRNPC promotes APP translation and stabilizes the APP precursors mRNA, which could suggest that increasing hnRNPC levels may promote Aβ secretion." (PMID 34924950, 2021). "Alzheimer’s disease is the most common neurodegenerative disease in the world and is characterized by the accumulation of beta-amyloid (Aβ) plaques from amyloid precursor protein (APP) and hyperphosphorylated tau protein." (PMID 33748103, 2021). "Understanding the spatiotemporal context in which Aβ is produced and accumulated may provide insight into pathogenicity of Aβ as well as therapeutic development targeted toward APP and Aβ for Alzheimer's disease." (PMID 33063327, 2021). "Additionally, the C terminal APP fragment has been shown to regulate lipid homeostasis by acting as a cholesterol sensor in the membrane, contributing to the early pathology in Alzheimer’s disease." (PMID 34692675, 2021). "Alzheimer’s disease (AD) is an irreversible form of dementia characterized by the deposition of amyloid beta (Aβ) through abnormal catabolism of amyloid precursor protein (APP) and the formation of neurofibrillary tangles (NFTs) of hyperphosphorylated tau." (PMID 34571815, 2021). "The APP intracellular domain that gets released in the cytoplasm and the extracellular released Aβ peptide that forms oligomers and large aggregates that accumulate in form of β-amyloid plaques in Alzheimer’s disease." (PMID 34202290, 2021). "APP, the amyloid-β precursor protein, is central to the pathogenesis of Alzheimer’s disease." (PMID 34151937, 2021). "Interestingly, a single torpor and arousal sequence was also sufficient to restore contextual fear memory in an APP/PS1 mouse model of Alzheimer’s disease." (PMID 34326412, 2021). "Similar to Alzheimer’s disease, sIBM patients present the pathological feature of sporadic inclusion body myositis, which is characterized by abnormal accumulation of amyloid precursor protein (APP) and its proteolytic fragment, amyloid-β (Aβ)." (PMID 33841177, 2021).
Alzheimer disease (continued). "Amyloid precursor protein (APP) processing is central to Alzheimer’s disease (AD) etiology." (PMID 34238366, 2021). "In this study, we set out to assess hippocampal-dependant learning in the APP/PS1 mouse model of Alzheimer’s disease (AD) on two highly translatable touchscreen tasks – the Paired Associate Learning (PAL) task and the Trial Unique Non-Matching to Location (TUNL) task." (PMID 34938165, 2021). "In summary, our results show that CMA activation by either Metformin treatment or overexpression of Hsc70 can decrease the insoluble Aβ1-42 burden, Aβ plaque levels, induce degradation of APP and alleviate cognitive deficits of the APP/PS1 model of Alzheimer’s disease." (PMID 34291435, 2021). "The proteolytic processing of amyloid precursor protein (APP) by β-secretase (BACE1) and γ-secretase releases amyloid-β peptide (Aβ), which deposits in amyloid plaques and contributes to the initial causative events of Alzheimer’s disease (AD)." (PMID 33804171, 2021). "In SH-SY5Y cells expressing amyloid precursor protein (APP) mutants, that are directly associated with the pathogenesis Alzheimer’s disease (AD), IXA4 increased targeting of APP to degradation in IRE1-dependent fashion, and thus contributed to reduced Aβ secretion and improvement of ER proteostasis." (PMID 33562589, 2021). "We demonstrate the utility of such a design by creating a molecular beacon reporter to detect amyloid‐β peptides, known to be involved in the pathogenesis of Alzheimer's disease, as they are produced from amyloid precursor protein (APP) along the endocytic pathway of living cells." (PMID 33063327, 2021). "In addition, DMDD also protected against apoptosis in PC-12 pheochromocytoma cells in vitro and APP/PS1 Alzheimer’s disease mice in vivo." (PMID 34975464, 2021). "In addition, in Alzheimer's disease, silybin-treated APP/PS1 transgenic mice showed higher numbers of newly generated microglia, astrocytes, neurons, and neuronal precursor cells, indicating its positive effects on neuro-regeneration." (PMID 34557140, 2021). "Importantly, APP is causally linked with Alzheimer’s disease and our observations suggest a previously unidentified link between synaptic FUS accumulation and APP misregulation." (PMID 34021139, 2021). "Moreover, J4 normalized multiple dysregulated canonical pathways, which were also observed in other Alzheimer's disease mouse models (Tg4510 and APP/PS1), in Tau22 mice." (PMID 34158119, 2021). "The goal of the present paper was to analyze studies exploring platelet APP metabolism in Alzheimer’s disease patients trying to assess potential reliable peripheral biomarkers, to offer new therapeutic solutions and to understand the pathophysiology of the AD." (PMID 34440494, 2021). "Finally, it would be therapeutically desirable to activate TspanC8/ADAM10 in some instances, for example, to induce cleavage of APP to treat Alzheimer’s disease." (PMID 34201472, 2021). "Amyloid precursor protein (APP) and β-Site APP cleaving enzyme 1 (BACE1) have also been identified as undergoing palmitoylation in neurons and are implicated in the pathogenesis of Alzheimer’s disease (AD)." (PMID 33430908, 2021). "CUR has several inhibitory effects on combining aging and Alzheimer's disease pathophysiology, such as the suppression of amyloid precursor protein (APP) and Aβ synthesis and the overexpression of ApoE and Nrf2 gene, as well as the prohibition of p-mTOR and p-NF-κB." (PMID 34692844, 2021). "In the APP/PS1 animal model of Alzheimer's disease, partial sleep deprivation could accelerate Aβ plaques depositions and cognition impairment." (PMID 34992526, 2021). "However, in contrast to APP duplication carriers, people with DS have only a 70% likelihood of developing Alzheimer's disease, suggesting the presence of protective genes on chromosome 21." (PMID 33539581, 2021).
Alzheimer disease (continued). "For example, a high-affinity interaction was reported between recombinant KLC1 and the Alzheimer’s disease-related amyloid precursor protein (APP), leading to the claim that APP might act as an adaptor protein linking conventional kinesin to MBO cargoes." (PMID 34234649, 2021). "Individuals with Down syndrome (DS) have an overabundance of amyloid-β (Aβ) peptide production due to trisomy of chromosome 21, which harbors the Aβ-precursor protein (APP) gene, and they typically develop Alzheimer’s disease (AD) pathology by the fifth decade of life." (PMID 34489686, 2021). "In Alzheimer’s disease, ADAM10 activation has the potential to inhibit disease progression, because ADAM10 cleavage of amyloid precursor protein (APP) prevents the generation of the pathogenic amyloid β peptide, which can otherwise be produced by β- and γ-secretases cleaving at alternative sites." (PMID 34201472, 2021). "BMECs are equipped to produce Aβ, expression and metabolism of APP in these cells is regulated by nitric oxide, and it might be relevant in the pathogenesis of cerebral amyloid angiopathy in Alzheimer’s disease." (PMID 33925080, 2021). "Alzheimer’s disease (AD) is neuropathologically characterized by the accumulation of Amyloid-β (Aβ) in senile plaques derived from amyloidogenic processing of a precursor protein (APP)." (PMID 34440266, 2021). "Thus, genes on chromosome 21, other than APP, likely modulate Alzheimer’s disease in people who have Down syndrome." (PMID 33707583, 2021). "2-Dodecyl-6-methoxycyclohexa-2,5-diene-1,4-dione (DMDD), an active compound was purified from the roots of Averrhoa carambola L. Previous studies have reported that DMDD improves cognitive impairment by protected against neuronal apoptosis in APP/PS1 Alzheimer’s disease mice." (PMID 34975464, 2021). "NAFLD induced Alzheimer disease in wild-type mice and in mice carrying the Swedish APP protein and the Δe9 presenilin 1 mutation but lacking mouse APP protein." (PMID 34204545, 2021). "Importantly, we find that in the APP/PS1 mouse model of Alzheimer’s disease (AD), activation of CMA by Hsc70 overexpression or Metformin potently reduces the accumulated brain Aβ plaque levels and reverses the molecular and behavioral AD phenotypes." (PMID 34291435, 2021). "Several lines of recent evidence indicate that the amyloid precursor protein-derived C-terminal fragments (APP-CTFs) could correspond to an etiological trigger of Alzheimer’s disease (AD) pathology." (PMID 33079262, 2021). "The amyloidogenic cleavage of the amyloid precursor protein (APP) results in the aggregation and accumulation of β-amyloid (Aβ) in senile plaques, which lead to inflammation, tauopathies, and consequent synaptic loss characteristic of Alzheimer’s disease (AD)." (PMID 33670873, 2021). "γ-Secretase was originally identified as the protease that carried out the final cleavage to release the amyloid beta (Aβ) from the amyloid β precursor protein (APP) and was an early target for pharmacologic inhibition of Aβ by γ-secretase inhibitors (GSIs) in Alzheimer’s disease (AD)." (PMID 32430033, 2020). "For example, in neurodegenerative diseases, there is a significant proportion (>10%) of monogenic families in whom the disease is caused by singular highly penetrant disease genes, e.g., LRRK2 and PRKN in Parkinson’s disease or PSEN1 and APP in Alzheimer ́s disease." (PMID 32854198, 2020). "A large fraction of the top pathways regardless of the miRNA direction were enriched for brain function and neurodegeneration, including “Downregulated in Alzheimer’s Disease” (p = 10−5), “regulation of synaptic transmission” (p = 0.028), and “APP catabolic processes” (p = 0.032)." (PMID 33235214, 2020). "The precise function of APP is unknown but it is involved in Alzheimer’s disease and also has been hypothesised to be involved in liver metabolism." (PMID 33138772, 2020).
Alzheimer disease (continued). "Exosomes isolated from hypoxia-preconditioned BM-MSCs could rescue synaptic dysfunction and promote anti-inflammatory effects in an APP/PS1 murine model of Alzheimer’s disease (AD)." (PMID 33246476, 2020). "Finally, we found that UMI-77 can induce mitophagy in vivo and that it effectively reverses molecular and behavioral phenotypes in the APP/PS1 mouse model of Alzheimer’s disease." (PMID 33184293, 2020). "The data suggest that the effect of moxibustion intervention on cognitive function in aging mice is related to the regulation of genes and proteins involved in APP metabolism pathway; this may be a potential target for treating Alzheimer's disease." (PMID 32855649, 2020). "Mouse models of Alzheimer’s disease commonly use the transgenic overexpression of genes involved in the production of amyloid β (APP, PSEN1/2) and/or Tau (MAPT) and many of these models have been shown to recapitulate the hyperphosphorylated tau tangles characteristic of disease." (PMID 32255788, 2020). "An orbitrap-based study of hippocampi, medial prefrontal cortices, and striata tissue in a mouse model of Alzheimer's disease reports administration of a tocotrienol-rich fraction of palm oil down-regulates hippocampi expression of the amyloid beta A4 protein (APP)." (PMID 32863845, 2020). "Therefore, we conducted systematic proteomic examinations on synaptosomes prepared from an amyloidogenic mouse model of Alzheimer’s disease (APP/PS1)." (PMID 32034429, 2020). "The beneficial effect of TRPC6 to Alzheimer’s disease was demonstrated by showing that stimulating TRPC6 or the store-operated Ca2+ entry improved hippocampal long-term potentiation of the APP-presenilin 1 mutant mice, an experimental model of Alzheimer’s disease." (PMID 33490083, 2020). "In consistency, APP/PS1 mouse model of Alzheimer’s disease also had decreased Allobaculum." (PMID 33292701, 2020). "For instance, we detected BRCA1 in Breast Cancer, Amyloid Precursor Protein (APP) in Alzheimer’s Disease, INS in A1C measurement and Type 2 Diabetes, PCSK9 in LDL cholesterol levels and SNCAIP in Parkinson’s Disease, and the circadian rhythm gene CRY2 in Morning vs. Evening chronotype." (PMID 32678846, 2020). "Finally, network analysis in MSA-C showed enrichment for β-amyloid related functional classes, including the known Alzheimer’s disease (AD) genes, APP and PSEN1." (PMID 32493431, 2020). "Besides participating in the pathogenesis of Alzheimer's disease due to the accumulation of amyloid-β peptide contributes, APP also plays a neuroprotective role in the synaptic transmission, plasticity, calcium signaling, and neuronal network activity." (PMID 33123575, 2020). "We propose that lipids are at the center of Alzheimer’s disease pathology based on their involvement in the blood-brain barrier function, amyloid precursor protein (APP) processing, myelination, membrane remodeling, receptor signaling, inflammation, oxidation, and energy balance." (PMID 32581851, 2020). "Recently, several pathophysiological functions of APP have been proposed in different human diseases such as neurodevelopmental, autism, amyotrophic lateral sclerosis, multiple sclerosis, Alzheimer’s disease, and cancer." (PMID 32760223, 2020). "In addition, when we investigated CNVs with a size < 100 kb, the amyloid beta precursor protein gene (APP) overlapped with a deletion from one patient with Alzheimer disease in this study." (PMID 32223758, 2020). "Indeed, mammalian SYT7 levels are post-transcriptionally modulated by γ-secretase proteolytic activity and APP, linking it to SV trafficking defects in Alzheimer’s disease." (PMID 32343229, 2020). "The inhibitory effect of vitamin D3 on gamma-secretase activity had been previously reported in the context of Alzheimer’s disease; in this respect, gamma-secretase, in addition to Notch, also cleaves the amyloid precursor protein (APP) to produce amyloid-beta." (PMID 32272884, 2020).